IGLV7-43 (immunoglobulin lambda variable 7-43)
Description:
V region of the variable domain of immunoglobulin light chains that participates in the antigen recognition. Immunoglobulins, also known as antibodies, are membrane-bound or secreted glycoproteins produced by B lymphocytes. In the recognition phase of humoral immunity, the membrane-bound immunoglobulins serve as receptors which, upon binding of a specific antigen, trigger the clonal expansion and differentiation of B lymphocytes into immunoglobulins-secreting plasma cells. Secreted immunoglobulins mediate the effector phase of humoral immunity, which results in the elimination of bound antigens. The antigen binding site is formed by the variable domain of one heavy chain, together with that of its associated light chain. Thus, each immunoglobulin has two antigen binding sites with remarkable affinity for a particular antigen. The variable domains are assembled by a process called V-(D)-J rearrangement and can then be subjected to somatic hypermutations which, after exposure to antigen and selection, allow affinity maturation for a particular antigen.
Synonyms: IGLV743; V3-2
Tractability: Antibody: its Gene Ontology location is reachable by antibodies, with high confidence; UniProt places it where antibodies can reach, with medium confidence; UniProt predicts a signal peptide or a membrane-spanning region.
Gene: Immunoglobulin variable (V) gene on chromosome 22 (22,395,018 to 22,395,489, forward strand). Ensembl gene ENSG00000211652.
Subcellular location: Secreted; Cell membrane
Pathways (Reactome):
Immune System: Antigen activates B Cell Receptor (BCR) leading to generation of second messengers; CD22 mediated BCR regulation; Classical antibody-mediated complement activation; FCERI mediated Ca+2 mobilization; FCERI mediated MAPK activation; FCERI mediated NF-kB activation; FCGR activation; Fc epsilon receptor (FCERI) signaling; Immunoregulatory interactions between a Lymphoid and a non-Lymphoid cell; Initial triggering of complement; Regulation of Complement cascade; Regulation of actin dynamics for phagocytic cup formation; Role of LAT2/NTAL/LAB on calcium mobilization; Role of phospholipids in phagocytosis
Disease: FCGR3A-mediated IL10 synthesis; FCGR3A-mediated phagocytosis; Potential therapeutics for SARS
Hemostasis: Cell surface interactions at the vascular wall
Vesicle-mediated transport: Scavenging of heme from plasma
Gene Ontology:
Molecular function: antigen binding
Biological process: immune response
Cellular component: extracellular region; immunoglobulin complex; plasma membrane
Homologues: Orthologues: macaque IGLV7-43 (74% identical). Paralogues in human: IGLV7-46 (91% identical), IGLV8-61 (62% identical), IGLV1-40 (50% identical), IGLV2-18 (49% identical), IGLV4-60 (49% identical), IGLV2-11 (48% identical), IGLV2-8 (48% identical), IGLV3-25 (48% identical), IGLV5-37 (48% identical), IGLV5-52 (48% identical), IGKV3D-7 (47% identical), IGLV1-44 (47% identical), and 81 more.
Diseases named in the same sentence as IGLV7-43 in open-access papers:
IGLV7-43 is named in the same sentence as 1 disease in open-access papers, as found by Europe PMC text mining. Sharing a sentence is not in itself a finding about the gene and the disease.
IGLV7-43 shares sentences with these, for which no sentence is quoted: tumor (1 paper).